NTN4 (netrin 4)
Diseases named in the same sentence as NTN4 in open-access papers (continued):
Sharing a sentence is not in itself a finding about the gene and the disease.
gastric cancer (7 papers, 2015 to 2024). A primary or metastatic malignant neoplasm involving the stomach. "On the contrary, studies have also reported high expression of NTN4 at both the tissue level and circulatory level in gastric cancer patients, where elevation in NTN4 was associated with the severity of pathological stages of gastric cancer." (PMID 37736464, 2023). "Bioinformatics analysis showed netrin-4 (NTN4) as a potential target of miR-210 to suppress gastric cancer cell migration." (PMID 38175202, 2024). "CD204+ M2-like TAMs can utilize the TNF-α/NF-κB/HIF-1α/miR-210/NTN4 pathway to facilitate gastric cancer progression." (PMID 38175202, 2024). "In conclusion, we have clearly demonstrated that CD204+ M2-like TAMs are able to suppress NTN4 expression by upregulating miR-210 in gastric cancer cells, thereby leading to increased cell migration." (PMID 38175202, 2024). "We further verified function of NTN4 in gastric cancer cells and found that treatment with human recombinant NTN4 inhibited coculture-induced migration of AGS cells." (PMID 38175202, 2024). "To determine the significance of miR-210 and NTN4 in gastric cancer, we measured their expression in tumor tissues, and carried out Kaplan–Meier to estimate overall survival." (PMID 38175202, 2024). "While a batch of evidence indicates the decreased expression of NTN4 in breast, pancreas, prostate, cervical, and colon cancer, elevated levels of this protein have also been documented in gastric cancer." (PMID 37736464, 2023). "In gastric cancer patients' tumor tissues and serum samples increased levels of NTN4 were, on the other hand, a biomarker correlated with a relatively poor survival rate." (PMID 30923634, 2019). "Here, we extended this work to gastric cancer and discovered Ntn4 was highly expressed in GC tissues." (PMID 25909166, 2015). "We then determined the function of NTN4 in gastric cancer cells." (PMID 38175202, 2024). "Previous reports have shown that endogenous NTN4 promotes cell migration in gastric cancer cells." (PMID 28038459, 2017). "Endogenous NTN4 also induces migration and proliferation in gastric cancer cells." (PMID 28038459, 2017). "Taken together, NTN4 might be a potential prognostic factor for gastric cancer." (PMID 38175202, 2024). "In other cell types, such as gastric cancer, NEO1 modulates the effect of endogenous NTN4 on motility." (PMID 28038459, 2017). "Together, these data indicated that OR3A4 upregulation contributes to metastasis and tumorigenesis in gastric cancer by regulating the activation of PDLIM2, MACC1, NTN4, and GNB2L1." (PMID 26863570, 2016). "Global microarray analysis combined with RT-PCR, RNA immunoprecipitation, and RNA pull-down analyses after OR3A4 transfection demonstrated that OR3A4 influenced biologic functions in gastric cancer cells via regulating the activation of PDLIM2, MACC1, NTN4, and GNB2L1." (PMID 26863570, 2016). "Therefore, OR3A4 overexpression may promote growth, invasion, metastasis, and tumorigenesis in gastric cancer in vitro and in vivo by upregulating MACC1 and GNB2L1 expression, and downregulating PDLIM2 and NTN4 expression." (PMID 26863570, 2016). "Similarly, we also found lower NTN4 mRNA expression in gastric tumor tissues compared with corresponding noncancerous tissues, and gastric cancer patients with high NTN4 expression had favorable survival, suggesting that NTN4 exerts a protective function against cancer progression." (PMID 38175202, 2024).
colorectal cancer (5 papers, 2014 to 2023). A primary or metastatic malignant neoplasm that affects the colon or rectum. "Netrin-4 overexpression decreases colorectal cancer progression in terms of liver metastasis number and size." (PMID 24472220, 2014). "Furthermore, NTN4 inhibits tumor progression in colorectal cancer by exerting anti-angiogenic effects." (PMID 37345154, 2023). "Interestingly, NTN4 shares the laminin domain with netrin-1 (NTN1), and there is evidence that NTN4 could exert its angiogenic roles via indirect interaction with the NTN1 putative receptors Unc-5 netrin receptor B (UNC5B) and Deleted in colorectal carcinoma (DCC)." (PMID 33923095, 2021).
endometrial cancer (4 papers, 2024 to 2025). Primary or metastatic malignant neoplasm involving the endometrium (mucous membrane that lines the endometrial cavity). "In endometrial cancer, the growth factor-like protein Netrin-4 (NTN4) promotes cancer stemness by activating c-Myc through the integrin β1/FAK/Src signaling pathway." (PMID 41373619, 2025). "Conversely, in endometrial cancer, NTN4 exhibits oncogenic properties." (PMID 41235257, 2025).
neuroblastoma (4 papers, 2016 to 2019). Neuroblastoma (NB) is the most common solid, extracranial childhood tumor. "Furthermore, NTN4 was shown to act as a cell adhesion molecule required for the migration induced by Neogenin-1 (NEO1) in SK-N-SH neuroblastoma cells." (PMID 30160193, 2019). "Public databases contain extensive information regarding the expression of NEO1 and its ligands Netrin-1 (NTN1) and Netrin-4 (NTN4) in primary neuroblastoma (NB) tumors." (PMID 28038459, 2017). "As MYCN amplification is associated with NB aggressiveness and poor prognosis (MYCN protein expression as a predictor of neuroblastoma prognosis), we evaluated the relation in between MYCN amplification and NEO1/NTN4 expression." (PMID 28038459, 2017). "Since the levels of DCC are low in cancer-derived cell lines, netrin-4 was used in these experiments, since this is an effective ligand for neogenin, which is abundant in SH-SY5Y neuroblastoma cells." (PMID 27716118, 2016).
colon cancer (3 papers, 2014 to 2024). "Overexpression of NTN-4 impaired tumor growth and angiogenesis in a mouse xenograft model of colon cancer." (PMID 38175202, 2024). "We reported previously that Netrin-4 overexpression in pancreatic tumor cells (PC3) and in colon cancer cells (LS174) delayed tumor angiogenesis in two mouse models of subcutaneous xenograft." (PMID 24472220, 2014).
liver fibrosis (3 papers, 2018 to 2021). "Another lncRNA, LTCONS_00038568, was shown to target netrin-4 (NTN4) and modulate liver fibrosis through inhibition of epithelial-mesenchymal transition (EMT)." (PMID 30477236, 2018). "Overall, the differential expression of 5,449 genes were detected and three genes which regulate the expression of connective tissue growth factor, fibroblast growth factor 2 and netrin 4, each associated with HSC activation and liver fibrosis, were identified." (PMID 34648138, 2021). "LTCONS_00038568 also possible to target NTN4 to improve liver fibrosis by reversal of EMT." (PMID 29495545, 2018). "Furthermore, several lncRNAs target genes that have been reported to associated with HSC activated and liver fibrosis, such as CTGF, FGF2, FGFR1, IGFBP7 and NTN4." (PMID 29495545, 2018). "Furthermore, one of the observation is that the expression levels of FGF2 and NTN4 increased in VPA (quiescent hHSC) and consistent with the previous report, which suggested that their targeted lncRNAs likely have these function in hepatic fibrosis." (PMID 29495545, 2018).
Cirrhosis (2 papers, 2023). A chronic disorder of the liver in which liver tissue becomes scarred and is partially replaced by regenerative nodules and fibrotic tissue resulting in loss of liver function. "The miR-17-92 cluster, which is upregulated in cirrhosis, is a well-characterized oncomiR due to its capacity to inhibit the expression of cAMP Responsive Element Binding Protein Like 2 (CREBL2), Proline Rich and Gla Domain 1 (PRRG1), and Netrin 4 (NTN4)." (PMID 38067261, 2023). "Additionally, we identified that HCC patients with Child-Pugh score C had significantly lower NTN4 levels compared to Child-Pugh score A and B patients, indicating the prognostic value of NTN4 in predicting advanced stages of liver injury in HCC patients with Child-Pugh C cirrhosis." (PMID 37736464, 2023).
Clear Cell Renal Cell Carcinoma (2 papers, 2023 to 2025). "In clear cell renal cell carcinoma (ccRCC), NTN4 inhibits tumor progression by regulating β-catenin expression and nuclear translocation." (PMID 41235257, 2025).
diabetes (2 papers, 2021 to 2023). "Collectively, our findings suggest that NTN4 contributes to DR regulating the immune response associated with diabetes and favoring an anti-inflammatory milieu." (PMID 33923095, 2021). "We further evaluated a knock-out model for NTN4 undergoing experimental diabetes induced by streptozotocin." (PMID 33923095, 2021). "The use of a systemic NTN4 knock-out permits understanding the consequences of the lack of NTN4 in a pathologic scenario such as diabetes, with local damage in the retina." (PMID 33923095, 2021). "Given that DR and, specifically, STZ-induced diabetes has a repercussion on visual acuity, we evaluated the function of retinal cell types by means of scotopic Ganzfeld electroretinography (ERG) in order to assess the impact of NTN4 in the diseased retina." (PMID 33923095, 2021).
Gilles de la Tourette Syndrome (2 papers, 2016 to 2021). "Additionally, both Neurexin 1 and Netrin 4 have also been implicated in the etiology of Tourette syndrome." (PMID 34207710, 2021).
glioma (2 papers, 2018 to 2024). A benign or malignant brain and spinal cord tumor that arises from glial cells (astrocytes, oligodendrocytes, ependymal cells). "Interestingly, a potential integrin-associated protein, netrin-4, is also highly expressed at the invading edge of glioma." (PMID 30514230, 2018).
ischemic stroke (2 papers, 2019 to 2026). A stroke disorder caused by obstruction of blood flow to the brain, due to thrombotic (local blood clot formation) or embolic (due to a blood clot or other material traveling from another site) event. "Several variants detected in this study demonstrated suggestive association with outcome (p < 10−5), some of which are within or near genes with experimental evidence of influence on ischemic stroke volume and/or brain recovery (e.g., NTN4, TEK, and PTCH1)." (PMID 30796134, 2019).
Knee Osteoarthritis (2 papers, 2024 to 2025). "In conclusion, this study provides compelling evidence that NTN4 plays a pivotal role in the progression of knee osteoarthritis through its contributions to inflammation, immune cell recruitment, and matrix degradation within the infrapatellar fat pad." (PMID 39518922, 2024).
melanoma (2 papers, 2016 to 2024). A malignant, usually aggressive tumor composed of atypical, neoplastic melanocytes. "NTN4 expression was significantly higher in most mesenchymal-like melanoma cells compared with epithelial-like melanoma cells." (PMID 27172792, 2016). "Although this study shows an association between PXDN, NTN4, GLIS3 and SNAI1 and melanoma invasion, their roles in melanoma are most likely multifaceted." (PMID 27172792, 2016). "Our previous GSEA of melanoma cell lines revealed that NTN4 was down-regulated in osteosarcoma cells following knockdown of HDAC2, suggesting that it is epigenetically regulated in cancer cells." (PMID 27172792, 2016). "Since PXDN, NTN4 and GLIS3 are involved in motility and associated with mesenchymal gene signature in melanoma cell lines, we investigated the association of these candidate proteins with markers of EMT in clinical samples." (PMID 27172792, 2016). "Silencing NTN4 reduced the invasive ability of mesenchymal-like melanoma cells compared with control siRNA treated cells in vitro." (PMID 27172792, 2016). "NTN4 was reported to enhance non-medullary thyroid cancer susceptibility, promote melanoma cell invasion, but inhibit primary and metastatic colorectal tumor progression." (PMID 39052013, 2024). "Furthermore, migration of PXDN, NTN4 or GLIS3 siRNA transfected melanoma cells was inhibited following transplantation into the embryonic chicken neural tube compared to control siRNA transfected melanoma cells." (PMID 27172792, 2016). "NTN4 siRNA treated melanoma cells from LM-MEL-44 and -53 predominantly remain at the site of injection and demonstrated a significant reduction in emigration from the neural tube in vivo into the surrounding tissue in the embryo in whole mount and cross-sections." (PMID 27172792, 2016). "Our data suggest a role for NTN4 in regulating melanoma invasion, and NTN4 being an ECM protein, peptides or antibodies that inhibit or limit its action might be among the strategies to control or limit melanoma metastasis." (PMID 27172792, 2016). "In this study we investigated three genes consistently upregulated in mesenchymal-like melanoma cells including Peroxidasin (PXDN), Netrin 4(NTN4) and GLIS Family Zinc Finger 3 (GLIS3)." (PMID 27172792, 2016). "The preceding experiments indicated that PXDN, NTN4 and GLIS3 are highly expressed in metastatic melanoma and play a role in promoting melanoma cell invasion in vitro." (PMID 27172792, 2016). "Given that PXDN, NTN4 and GLIS3 can regulate invasion of melanoma cells in vitro, we evaluated the in vivo relevance of our data in melanoma tumors." (PMID 27172792, 2016). "We then analysed the protein expression patterns of PXDN, NTN4 and GLIS3 in melanoma tumors by immunohistochemical staining of tissue microarrays (TMA) comprising tumors from patients with stage III and IV metastatic melanoma." (PMID 27172792, 2016). "We identified Peroxidasin (PXDN), Netrin 4 (NTN4) and GLIS Family Zinc Finger 3 (GLIS3) genes consistently elevated in invasive mesenchymal-like melanoma cells." (PMID 27172792, 2016). "Melanoma cells were transfected with siRNA targeting PXDN, NTN4 or GLIS3, cultured as a hanging drop for 24 hours and introduced into the trunk neural tube of a developing chick embryo." (PMID 27172792, 2016). "Through a knockdown approach and in vivo motility model, we demonstrate 3 novel molecular players PXDN, NTN4 and GLIS3 as critical factors of melanoma invasion." (PMID 27172792, 2016). "Our study suggests that PXDN, NTN4 and GLIS3 play a functional role in promoting melanoma cellular invasion, and therapeutic approaches directed toward inhibiting the action of these proteins may reduce the incidence or progression of metastasis in melanoma patients." (PMID 27172792, 2016).
ovarian carcinoma (2 papers, 2020 to 2024). A malignant neoplasm originating from the surface ovarian epithelium. "NTN4 was present in ovarian cancer cells, and its corresponding receptor, UNC5B, was identified in fibroblasts." (PMID 39135097, 2024).
prostate carcinoma (2 papers, 2014 to 2020). A carcinoma that arises from epithelial cells of the prostate gland. "Tumor blood vessel maturation was assessed in nude mice subcutaneously xenografted with human PC3 (prostate cancer) cells overexpressing Netrin-4." (PMID 24472220, 2014).
rheumatoid arthritis (2 papers, 2024 to 2025). A chronic, systemic autoimmune disorder characterized by inflammation in the synovial membranes and articular surfaces. "A recent study reported a possible association between NTN4 and pain in patients with rheumatoid arthritis, noting that it augments the branching of sensory neurons." (PMID 40136644, 2025). "Although Netrin-4 (NTN4) has been implicated in pain modulation in rheumatoid arthritis (RA), its role in OA pain remains less understood." (PMID 40136644, 2025). "Previous research has demonstrated that fibroblast-secreted NTN4 facilitates axonal and neurite growth, supporting a mechanistic link between NTN4 and pain propagation in rheumatoid arthritis." (PMID 40136644, 2025). "Previous study reported that NTN4 is abundantly expressed by lining fibroblast in synovium derived from rheumatoid arthritis patients." (PMID 39518922, 2024). "Additionally, a recent study reported that NTN4 expression in synovial fibroblast derived from rheumatoid arthritis patients correlated with pain." (PMID 39518922, 2024).
triple-negative breast carcinoma (2 papers, 2020 to 2022). An invasive breast carcinoma which is negative for expression of estrogen receptor (ER), progesterone receptor (PR), and human epidermal growth factor receptor 2 (HER2). "In different molecular subtypes, luminal had higher mRNA expression of NTN4 than HER2+ and triple negative breast cancer (TNBC) (P < 0.001)." (PMID 35732855, 2022).
Anxiety (1 paper, 2026). Intense feelings of nervousness, tension, or panic often arise in response to interpersonal stresses. "Conditional endothelial deletion of Ntn4 in mice impaired spatial memory, induced anxiety-like behavior, and reduced mature oligodendrocytes, accompanied by disrupted myelin ultrastructure." (PMID 41536029, 2026).
astrocytoma (1 paper, 2025). "In contrast, G.2 and G.3 astrocytoma samples showed elevated expression of NTN4/netrin-4 protein in vascular basement membranes and in some TCs, which confirms the transcript expression data." (PMID 41366031, 2025).
Breast Invasive Ductal Carcinoma (1 paper, 2022). "Among Breast Invasive Ductal Carcinoma, amplification in NTN4 was common." (PMID 35732855, 2022).
Breast Invasive Lobular Carcinoma (1 paper, 2022). "Among Breast Invasive Lobular Carcinoma, amplification and mutation of NTN4 occurred with an equal frequency as well." (PMID 35732855, 2022).
breast tumor (1 paper, 2012). "Lymphatic vessels associated with breast tumors express netrin-4, and LECs show enhanced proliferation, migration, and tube formation in response to netrin-4." (PMID 22505936, 2012). "Inhibition of α6β1 blocks LEC migration on netrin-4, and α6β1 colocalizes with netrin-4 in lymphatic vessels during embryogenesis, in adult intestine, and in breast tumor xenografts." (PMID 22505936, 2012).
Cerebral ischemia (1 paper, 2021). Restriction of arterial blood supply to the brain associated with insufficient oxygenation to support the metabolic requirements of the tissue. "Alternatively, a study on cerebral ischemia demonstrated that after stroke, NTN4 is upregulated in astrocytes and blood vessels of the ischemic core, and DCC but not UNC5B is upregulated in neuronal processes." (PMID 33923095, 2021).
endometriosis (1 paper, 2020). The growth of functional endometrial tissue in anatomic sites outside the uterine body. "A study was shown that in endometriosis macrophage-derived Netrin-1 was vital for neuro-angiogenesis while another shown that Netrin-4 was crucial for maintaining blood vessel by regulating endothelial and perivascular cells." (PMID 33088218, 2020).
gastric tumor (1 paper, 2024). "NTN4 mRNA expression was lower in gastric tumor tissues than in noncancerous parts." (PMID 38175202, 2024).
gynecological cancers (1 paper, 2024). "In addition to two genes (CXCL14 and NTN4) that were differentially expressed in the NR group compared with that in the R group, those included in the significant LR pair only in the NR group were associated with a good prognosis of ovarian or other gynecological cancers." (PMID 39135097, 2024).
hepatocellular carcinoma (1 paper, 2023). A malignant tumor that arises from hepatocytes. "NTN4: netrin-4; HCC: hepatocellular carcinoma; AFP: alpha-fetoprotein; PVI: portal vein invasion; IQR: interquartile range; p-value < 0.05 is statistically significant; * metastasis (intrahepatic and extrahepatic)." (PMID 37736464, 2023). "NTN4: netrin-4; HCC: hepatocellular carcinoma; IQR: interquartile range; p-value < 0.05 is statistically significant." (PMID 37736464, 2023). "r = coefficient of correlation; NTN4: netrin-4; HCC: hepatocellular carcinoma; AST: aspartate transaminase; γGT: gamma-glutamyl transferase; ALP: alkaline phosphatase; * p < 0.05 is a statistically significant correlation." (PMID 37736464, 2023).
injury (1 paper, 2021). Damage inflicted on the body as the direct or indirect result of an external force, with or without disruption of structural continuity. "We directly administered anti-Netrin-4 antibody to the cisterna magna to examine whether anti-Netrin-4 antibody, which has an analgesic effect on neuropathic pain caused by sciatic nerve injury, exerted an analgesic effect on neuropathic pain caused by infraorbital nerve injury." (PMID 33914819, 2021).